PCDHGA2 (protocadherin gamma subfamily A, 2)
Description:
Potential calcium-dependent cell-adhesion protein. May be involved in the establishment and maintenance of specific neuronal connections in the brain.
Synonyms: PCDH-gamma-A2
Tractability: Antibody: UniProt places it where antibodies can reach, with medium confidence; UniProt predicts a signal peptide or a membrane-spanning region; its Gene Ontology location is reachable by antibodies, with medium confidence; the Human Protein Atlas places it where antibodies can reach. PROTAC: its protein half-life has been measured.
Gene: Protein-coding gene on chromosome 5 (141,338,760 to 141,512,975, forward strand). Ensembl gene ENSG00000081853.
Subcellular location: Cell membrane
Subcellular location (Human Protein Atlas): Plasma membrane; Vesicles; Cytosol; Focal adhesion sites; Nucleoli; Nucleoplasm
Gene Ontology:
Molecular function: cell adhesion molecule binding; calcium ion binding
Biological process: cell adhesion; homophilic cell-cell adhesion
Cellular component: plasma membrane; membrane
Genetic constraint (gnomAD): Loss-of-function variants: 40 observed, 62.28 expected, observed/expected ratio (o/e) 0.64, 90% interval 0.5 to 0.84. The upper end of that interval is the gene's LOEUF score, 0.84, which puts it in group 3 of 6, group 1 being the genes least tolerant of losing a copy. Missense variants: 1,226 observed, 1,273.6 expected, observed/expected ratio (o/e) 0.96, 90% interval 0.92 to 1.01. Synonymous variants: 560 observed, 558.07 expected, observed/expected ratio (o/e) 1, 90% interval 0.94 to 1.08.
Homologues: Orthologues: mouse Pcdhga2 (86% identical). Paralogues in human: PCDHGA3 (78% identical), PCDHGA1 (76% identical), PCDHGA10 (75% identical), PCDHGA6 (75% identical), PCDHGA5 (75% identical), PCDHGA4 (75% identical), PCDHGA7 (74% identical), PCDHGA8 (73% identical), PCDHGA12 (73% identical), PCDHGA9 (72% identical), PCDHGA11 (71% identical), PCDHGB2 (50% identical), and 49 more.
Diseases named in the same sentence as PCDHGA2 in open-access papers:
PCDHGA2 is named in the same sentence as 6 diseases in open-access papers, as found by Europe PMC text mining. Sharing a sentence is not in itself a finding about the gene and the disease. The quoted sentences say what the papers report.
vascular malformation (1 paper, 2021). A non-neoplastic disorder that is the result of defects of vascular morphogenesis. "Assuming a spontaneous de novo mutation event, one of the identified variants found in the PREX1, UBE3B, PCDHGA2, and ZSWIM6 genes may represent a possible candidate pathogenic variant for this rare form of vascular malformation." (PMID 33652974, 2021).
tumor (2 papers, 2009 to 2015). "Here, subtype‐specific events involving either DNA copy number loss or CpG promoter methylation were found to involve TENC1, RARA, PCDHB11, PCDHB14, PCDHGA2 and PCDHGB2 indicative of candidate tumor suppressor genes in this context." (PMID 25468711, 2015). "These include PCDHGA3, hypermethylated in 24/27 tumours (89%), PCDHGB4 (23/25, 92%), PCDHGA2 (11/13, 85%) and PCDHB3 (21/33, 64%)." (PMID 19956686, 2009).
PCDHGA2 also shares sentences with these, for which no sentence is quoted: brain tumors (1 paper); breast carcinoma (1); cancer (1); Sotos syndrome (1).